PIEZO1 (piezo type mechanosensitive ion channel component 1 (Er blood group))
Diseases named in the same sentence as PIEZO1 in open-access papers (continued):
Sharing a sentence is not in itself a finding about the gene and the disease.
tumor (continued). "(A) MC38 tumor cells were implanted subcutaneously in WT and Piezo1-/- mice (n=10), IL-12 100 ng or anti-TGFβ1 mAb 200 ng per mouse in 50 μl volume or vehicle (PBS) was locally injected into tumor once a week and tumor size was measured every 5 days for 40 days." (PMID 35993548, 2022). "(D) MC38 OVA tumor cells were implanted subcutaneously in WT and Piezo1-/- mice (n=10) and at day 20, the CD45.1+ donor CFSE+OTII CD4+T cells were transferred into WT and Piezo1-/- tumor-bearing mice for 10 days." (PMID 35993548, 2022). "Moreover, Piezo1 reduction promotes NSCLC cell migration in A549 cells and facilitates tumor growth in nude mice." (PMID 36230880, 2022). "Although the desmoplastic tissue of PDAC exerts a massive mechanical stress onto the cells, the marked tissue acidosis in the tumor core renders Piezo1 less responsive, thus less active in PSCs and cells do not undergo cell death." (PMID 32116794, 2020). "Thus, PIEZO1’s positive correlation with these checkpoints suggests it may create an immunosuppressive TME, leading to rapid tumor progression." (PMID 40977743, 2025). "Interestingly, PRAD patients with no residual tumor (R0) had higher PIEZO1 expression than those with R1 and R2." (PMID 40977743, 2025). "Specifically, PIEZO1, a mechanically-gated cation channel protein, regulates the expression of extracellular matrix (ECM) remodeling genes such as TAZ and FHL3, resulting in ECM stiffening, alteration of the tumor microenvironment, and enhancement of tumor malignancy." (PMID 40535121, 2025). "As a mechanosensory protein, PIEZO1 may respond to external forces and participate in the modulation of the TME and cytoskeletal reorganization to establish an environment that physically inhibits CD8+ and CD4+ T cells from penetrating the tumor." (PMID 38398074, 2024). "In addition, immunohistochemistry (IHC) of resected tumor sections showed the expression of Ki67, PIEZO1, FAK, p-FAK, Akt and p-Akt in tumor tissues with or without circZNF800 knockdown." (PMID 38324181, 2024). "However, the signaling pathway between Piezo1 and YAP/TAZ complex is still unclear, and whether there is a synergistic effect between them in the process of tumor cell proliferation is still a question that needs to be further explored." (PMID 38690080, 2024). "Finally, we determined knocking down circZNF800 could decrease the expressions of PIEZO1, Ki67, p-FAK and p-Akt in tumor tissues." (PMID 38324181, 2024). "Of note, IGFBP1 depletion did not influence PIEZO1 expression in confined tumor cells." (PMID 37296072, 2023). "However, Piezo1 expression induction through YAP signaling is not relevant for the clinical T (tumor size) stage, histological grade, or lymph node metastasis." (PMID 36837670, 2023). "Besides Piezo1, another mechano-sensitive ion channel TRPV4 is involved in tumor progression." (PMID 35331296, 2022). "We further explored whether PIEZO1 was differentially expressed between tumor and normal tissues in the absence of data of normal tissue in TCGA." (PMID 35747124, 2022). "Targeting PIEZO1 by conjugating its monoclonal antibody with small molecular chemicals such as MMAE can efficiently suppress ESCC tumor cell growth both in vivo and in vitro without inducing any obvious side effects, which represents a promising strategy for improving ESCC patients' prognosis." (PMID 35608274, 2022). "Piezo1 could also upregulate the expression of histone deacetylase 2 (HDAC2), which suppresses Rb1 via epigenetic silencing, thereby expanding MDSCs and conferring a tumor immunosuppressive microenvironment." (PMID 36230880, 2022). "A previous study showed that Piezo1 regulated the assembly of focal adhesion, activation of integrin signaling and expression of a number of genes involved in ECM remodeling, further increased tissue stiffness, which in turn activated Piezo1 and elevated the mechanosensory capacity of tumor cells." (PMID 36112948, 2022).
tumor (continued). "Indeed, Anti‐PIEZO1‐MMAE showed tremendous toxicity to TE‐1 even at very low concentrations (IC50: 9040pM), whereas Anti‐PIEZO1 alone or IgG‐MMAE had no tumor suppression effect at the same concentrations." (PMID 35608274, 2022). "Because of this protective effect, PSCs may survive to migrate into the well-perfused invasive border of the tumor, where Piezo1 is fully responding to mechanical cues due to the lack of protonation-caused inhibition." (PMID 32116794, 2020). "Additionally, PIEZO1 was shown to be involved in tumour progression by serving as the central checkpoint of multiple ECM remodelling-related signalling pathways to modulate tumour cell proliferation and the tumour microenvironment in turn." (PMID 32999349, 2020). "Although the functional roles of Piezo1 may vary across different cancer types—regulating specific processes such as proliferation, migration, invasion, and epithelial–mesenchymal transition (EMT)—it commonly promotes cancer cell metastasis and invasion by altering tumor cell mechanical behavior." (PMID 40821847, 2025). "Moreover, the tumor weights and volumes were significantly increased in the ITGB1OE and Piezo1OE groups, while no significant changes were observed in the body weight of mice among each group, further supporting the notion that the Piezo1/ITGB1 axis contributed to tumor progression." (PMID 40667648, 2025). "In addition to the mechanical sensing pathway relied on by Piezo1, increased ECM stiffness can also directly compress intratumoral blood vessels, affecting their morphological structure and physiological functions, and participate in the regulation of tumor angiogenesis." (PMID 41226585, 2025). "Moreover, Piezo1 also promotes tumor metastasis by activating the non-Smad pathway of TGF-β." (PMID 38690080, 2024). "Additionally, the lack of precision in Piezo1 modulation (e.g., timing and dosage) and tumor heterogeneity further hinder clinical translation; moreover, long-term application of modulators may induce drug resistance, exacerbating these translational challenges." (PMID 41607548, 2026). "There is evidence to suggest that the combination of Piezo1 antibody and MMAE can not only promote tumor cell cycle arrest and apoptosis, but also slow down the development of ESCC xenograft tumor models without any side effects." (PMID 38690080, 2024). "Anti‐PIEZO1‐MMAE can induce cell cycle arrest and apoptosis of ESCC cells in vitro and suppress ESCC tumor cell growth in vivo without any obvious side effects." (PMID 35608274, 2022).
cancer (120 papers, 2012 to 2026). A tumor composed of atypical neoplastic, often pleomorphic cells that invade other tissues. "A comprehensive literature review was conducted, focusing on the specific mechanisms through which Piezo1 regulates endothelial cells, immune cells, cancer-associated fibroblasts and the extracellular matrix within the TME." (PMID 41437911, 2026). "Matrix stiffening profoundly influences cancer cell functions and cancer progression, and the mechanosensitive Piezo1 channel is implicated in these processes." (PMID 41585435, 2026). "PIEZO1 shows high diagnostic accuracy (AUC > 0.7) in 16 cancer types, supporting its role as a pan-cancer diagnostic biomarker." (PMID 40977743, 2025). "Significantly, Piezo1 is highly expressed in the majority of cancer types and is linked to poor survival outcomes." (PMID 40643464, 2025). "Employing Receiver Operating Characteristic (ROC) curves, we calculated the Area Under Curve (AUC) to evaluate the diagnostic value of PIEZO1 across 33 cancers." (PMID 40977743, 2025). "Among these, PIEZO1 has emerged as a critical regulator of mechanotransduction in cancer, previously implicated in responses to shear stress, membrane stretch, and compression." (PMID 40890143, 2025). "Overexpression of PIEZO1 has been reported in multiple human cancers and is commonly associated with unfavorable prognosis." (PMID 40724850, 2025). "Our analysis revealed that PIEZO1 has diagnostic and prognostic value across different cancer types." (PMID 40977743, 2025). "Our study revealed that PIEZO1 exhibited positive association with StromalScore, ImmuneScore, and ESTIMATEScore in pan-cancer, highlighting its connection to both stromal and immune cells within the immune microenvironment." (PMID 40977743, 2025). "Piezo1 binds to matrix adhesion regions in a force-dependent manner via a linker domain and this binding is abrogated in cancer cells causing transformation to malignant phenotypes." (PMID 38393325, 2024). "Many studies have reported that Piezo1 is associated with many signaling pathways involved in cancer metastasis, such as angiogenesis, cell migration, and proliferation." (PMID 38463518, 2024). "Meanwhile, the PIEZO1 upregulation and cancer‐associated fibroblast (CAF) enrichment were found in GC progression." (PMID 37983931, 2023). "This study evidenced the relationship between the PIEZO1 expression level and the immune infiltration of endothelial cells and cancer-associated fibroblasts in most tumors." (PMID 35747124, 2022). "In this review, we summarize current knowledge regarding the role of Piezo1 in regulating cancer hallmarks and the underlying molecular mechanisms." (PMID 36230880, 2022). "This is an interesting dichotomy, as numerous studies have implicated Piezo1 as a driver of cancer progression and many pro-metastatic processes." (PMID 36080197, 2022). "PIEZO1 expression was linked with immune cell infiltration, such as endothelial cell and cancer-associated fibroblast." (PMID 35747124, 2022). "Calcium-gated ion channels, such as transient receptor potential cation channel subfamily V member 4 (TRPV4), P2X purinoceptor 7 (P2X7), and Piezo1, have recently been implicated as integral components in mechanisms of cancer metastasis and cell death." (PMID 36080197, 2022). "We analyzed types and sites of genetic mutation of PIEZO1 in different cancers within the TCGA database." (PMID 35747124, 2022). "We also found that epithelial-mesenchymal transition (EMT) hallmark was significantly enriched in high-PIEZO1 subgroups in most cancers." (PMID 35747124, 2022). "Piezo1-dependent mechanosensation has also been linked to immune regulation in the differentiation of suppressive myeloid cells that regulate cancer and infectious diseases." (PMID 33935792, 2021).
cancer (continued). "ERK1/2 has been linked to cancer progression and successful colony formation In one study, Piezo1 was activated by stretching the substrate on which the cells were cultured, causing deformation of the cell membranes." (PMID 34831037, 2021). "Piezo1 has also been linked to apoptosis in cancer cells and other cell types primarily through calpain-mediated apoptosis." (PMID 34831037, 2021). "This study demonstrated that cyclic stretching of the cancer cells caused a Piezo1-mediated calcium influx that resulted in Bax activation and intrinsic apoptosis." (PMID 34831037, 2021). "Altered Piezo1 expression is associated with several aggressive cancers including breast cancer, gliomas and squamous cell carcinoma." (PMID 33994356, 2021). "We then detected PIEZO1 association with clinical features across different cancer types." (PMID 40977743, 2025). "PIEZO1, a mechanosensitive ion channel, has been implicated in cancer progression, but its prognostic relevance in ccRCC remains unclear." (PMID 40724850, 2025). "To further explore the possible mechanisms of how PIEZO1 may contribute to worse clinical responses in HR-negative breast cancer, we investigated whether there is an association between PIEZO1 and the anti-cancer immune response in HR-negative breast cancer." (PMID 38398074, 2024). "Piezo1 has been linked to inflammation and immune surveillance in cancer." (PMID 37781915, 2023). "Moreover, Piezo1 causes inhibition of fibroblast formation and therefore supports even more invasion and migration of cancer cells." (PMID 36837670, 2023). "Loss of Piezo1 in bone marrow cells has been shown to prevent cancer." (PMID 37366640, 2023). "In addition, recent reports have associated aberrant Piezo1 with poor prognosis in certain types of cancer." (PMID 35942515, 2022). "Multiple studies have shown that PIEZO1 may become a reliable diagnostic and prognostic marker in different human cancers." (PMID 35747124, 2022). "Furthermore, Piezo1 is highly expressed in various tumors and is associated with poor prognoses in most cancers." (PMID 36230880, 2022). "Moreover, the strong link between PIEZO1 expression and stromal signatures identified in our dataset reflects similar associations described in their study, particularly with endothelial cells and cancer-associated fibroblasts." (PMID 40724850, 2025). "Moreover, Piezo1 can inhibit the recruitment and expansion of myeloid derived suppressor cells (MDSCs), a heterogeneous cell population with immunosuppressive function and significantly associated with poor cancer prognosis." (PMID 38690080, 2024). "In a word, this work establishes Piezo1-mediated mechano-chemotherapy as a readily translatable strategy, transforming mechanical force into a safe and effective tool for optimizing cancer treatment." (PMID 41782384, 2026). "Mounting evidence suggests a positive correlation between ECM stiffening-induced Piezo1 activation and cancer progression." (PMID 41437911, 2026). "This establishes a positive feedback loop between Piezo1-dependent mechanotransduction and abnormal tissue mechanics, promoting cancer progression." (PMID 41437911, 2026). "The assumption that Piezo1 modulation will selectively benefit antitumor immunity is flawed, as Piezo1 is frequently upregulated in various cancer types, where its activation promotes proliferation, invasion, and chemoresistance." (PMID 41607548, 2026). "In most cancers, the expression of Piezo1 channel is up-regulated and positively related to cancer cell migration." (PMID 41585435, 2026). "These diverse functions not only highlight the role of Piezo1 as a central hub in cancer mechanobiology but also lay the foundation for subsequent discussions on its therapeutic challenges and evidence hierarchy." (PMID 41607548, 2026). "A more significant challenge, however, is the pro-tumorigenic role of Piezo1 itself in cancer cells." (PMID 41607548, 2026).
cancer (continued). "Piezo1 is involved in the regulation of multiple diseases, including bone metabolism disorders, fibrosis, cancer, and cardiovascular diseases." (PMID 41017814, 2025). "This distinction suggests that targeting Piezo1 requires different therapeutic strategies, depending on the cancer type." (PMID 41017814, 2025). "The analysis in this study aims to provide a deeper understanding of the rearrangement of Piezo1 and to elucidate the distinctions between epithelial and cancer cells." (PMID 40727658, 2025). "This first pan-cancer analysis reveals PIEZO1’s differential expression across malignancies and its diagnostic/prognostic biomarker potential." (PMID 40977743, 2025). "Piezo1, also known as FAM38A, is a mechanically activated ion channel protein implicated in the pathogenesis of various cancers." (PMID 40667648, 2025). "This review summarizes emerging insights into Piezo1’s role in cancer progression and immune regulation and highlights its translational potential as a novel target in cancer immunotherapy." (PMID 40821847, 2025). "It has been shown that Piezo1 expression is higher in most cancer cells compared to normal cells leading to higher sensitivity of cancer to mechanical stress." (PMID 40727658, 2025). "In cancer cells, the activation of PIEZO1 play a prominent role in the malignant progression of cancer." (PMID 41227352, 2025). "After adjusting for age, high expression of PIEZO1 remained a significant predictor of prognosis across multiple cancer types." (PMID 40977743, 2025). "Several studies have demonstrated that Piezo1 is upregulated in multiple types of cancer, including breast, liver, and lung cancer." (PMID 40667648, 2025). "In this context, cross-cancer comparisons provide valuable insight into conserved and tissue-specific roles of candidate regulators such as PIEZO1." (PMID 40724850, 2025). "PIEZO1-mediated silencing of the retinoblastoma gene Rb1 drives immunosuppressive myelopoiesis in cancer and infectious disease." (PMID 40454475, 2025). "Our findings highlight PIEZO1’s critical role in cancer cell migration, consistent with prior studies." (PMID 40977743, 2025). "Secondly, PIEZO1 genomic alterations were present in 4% (92/2565) of pan-cancer patients and significantly correlated with m6A-related genes." (PMID 40977743, 2025). "Further examination revealed mutation, amplification, and deep deletion as the most prevalent forms of PIEZO1 gene modifications across various cancer types." (PMID 40977743, 2025). "An intriguing study by Cai and colleagues has indicated that cell sorting and burst-like movement caused by the stiffness of the ECM are reliant on E-cadherin, which aids the activity of Piezo1 during the movement of cancer cells." (PMID 40643464, 2025). "Apart from cancer cell mechanotransduction, there is also a judge impact of PIEZO1 signaling in immune cells, such as natural killer (NK) cells." (PMID 41227352, 2025). "The bending of the bilayer surrounding Piezo1 molecules is significantly increased in cancer cells, in contrast to epithelial cells." (PMID 40727658, 2025). "Crucially, Piezo1/ITGB1 overexpression promoted cancer development by suppressing apoptosis and enhancing proliferation." (PMID 40667648, 2025). "Collectively, our results position PIEZO1 as a promising biomarker for both diagnosis and prognosis in pan-cancer." (PMID 40977743, 2025). "The mechanosensitive Piezo1 channel has a critical role during this transduction in multiple cancer models, including gastric, breast, prostate, glioma, and osteosarcoma cancers." (PMID 40507332, 2025). "During cancer cell movement, activating Piezo1 improves the capacity of cancer cells to travel when pressured and squeeze through tight spaces by causing a shift from F-actin-driven pseudopods over to bleb-facilitated cell motility." (PMID 40643464, 2025).